RETN (resistin)
Diseases named in the same sentence as RETN in open-access papers (continued):
Sharing a sentence is not in itself a finding about the gene and the disease.
cancer (continued). "LA-TAMs also participated in the modification of cancer cells by SPP1, VEGFA, RETN, GRN, ADGRE5, and HBEGF secretion." (PMID 37649596, 2023). "It was shown that resistin reduces the expression of the proapototic genes FADD, FAS, and CASP8 in ovarian cells which promote the growth of cancer." (PMID 35453670, 2022). "Although this correlation is not well-understood, it is known that resistin promotes epithelial and mesenchymal multiplication in the breast parenchyma, which are critical mechanisms for tumor development and metastasis, and also can be related to cancer associated chronic inflammation." (PMID 32903534, 2020). "Therefore, although we have not yet determined the precise role of ICAM-1 and VCAM-1 expression in CRC cells, ICAM-1 and VCAM-1 in the resistin-treated cancer and endothelial cells may be secreted into the cancer microenvironment and mediate the interactions of cancer, immune, and endothelial cells." (PMID 26690142, 2015). "While no other published studies have examined resistin in infections, our finding of elevated resistin in the disease state agreed with prior studies showing elevations in gastrointestinal cancers, direct correlations between resistin and cancer stage and resistin and BMI loss." (PMID 23358528, 2013). "The expression of the key adipokines adiponectin, adipisin, leptin, resistin, and visfatin were significantly decreased by the cancer cells irrespective of the diet in the OFB, but not in the other adipose tissues." (PMID 38264656, 2023). "In turn, no significant gender-related differences in the resistin level were reported in the case of some cancer types that mainly affect males." (PMID 35453670, 2022). "Non-malignant tissue can show how resistin levels change as the cancer progresses, but does not serve as a normal control as tissue from healthy women would." (PMID 27314854, 2016). "Although accumulating evidence suggests that resistin plays an important role in the progression of cancers, the molecular mechanisms by which it acts has not been fully evaluated." (PMID 26729407, 2016). "However, the present study shows that resistin not only induces ICAM-1 and VCAM-1 expression in CRC cells but also mediates cancer cell adhesion to the endothelium." (PMID 26690142, 2015). "Though this hormone has been studied in cancer, we found no data on resistin in infection-related cachexia." (PMID 23358528, 2013). "Similarly, RETN can facilitate EMT and sustain cancer stemness through CAP1-dependent mechanisms." (PMID 41383622, 2025). "In this line, it has been established that in breast cancer, resistin induced the phosphorylation of proto-oncogene tyrosine-protein kinase Src (c-Src), protein phosphatase 2A (PP2A), and protein kinase C alpha (PKCα), among others, promoting cancer progression." (PMID 37238961, 2023). "Thus, the issue of whether the resistin-initiated endothelial adhesion of CRC cells through ICAM-1 and VCAM-1 in CRC cells is controlled by cancer cell-leukocyte interactions warrants further investigation." (PMID 26690142, 2015). "The potential role of resistin, adiponectin, and apelin in in gastroesophageal cancer (GEC) and their influence on cancer progression and cachexia syndrome are not entirely explained." (PMID 25049439, 2014). "However, there is no detailed information about whether resistin induces ICAM-1 and VCAM-1 expressions in cancer cells, and hence promotes its adhesion and invasion of the endothelium." (PMID 24555415, 2014).
cardiovascular disease (91 papers, 2007 to 2025). "The international literature reports clinical studies in humans demonstrating an association between both systemic and local resistin expression and cardiovascular diseases." (PMID 40283140, 2025). "The findings presented here also highlight the potential clinical applications of Rb1 in controlling resistin-associated vascular injury and the possible therapeutic use in cardiovascular disease." (PMID 37304947, 2023). "A recent MR research revealed the causal role of resistin in the development of cardiovascular disease, which probably acted through blood pressure." (PMID 36072663, 2022). "Previous studies reported associations between elevated circulating resistin levels and increased risk of cardiovascular disease." (PMID 36046788, 2022). "Under this scenario, resistin would be an important mediator of the deleterious effect of reduced kidney function on the risk of cardiovascular disease." (PMID 25811174, 2015). "This is the first study showing that high serum resistin (a likely consequence, at least partly, of increased RETN expression) is a risk factor for cardiovascular disease and all-cause mortality in diabetic patients of European ancestry." (PMID 23755138, 2014). "In the present study, the association between serum resistin concentration and cardiovascular disease (CVD) was investigated in a general Japanese population." (PMID 19922611, 2009). "For example, a sedentary routine has been described to induce resistin and leptin as well as reduced plasma levels of adiponectin, which may promote cardiovascular disease, while regular exercise can mitigate such adipokine risk response." (PMID 39861386, 2025). "Recent studies suggest that resistin may directly cause endothelial dysfunction and has been associated with coronary heart disease and cardiovascular disease (CVD)-related mortality." (PMID 39184804, 2024). "Additionally, RETN’s SNP rs3745367 has been implicated in cardiovascular disease, resistin levels, fasting glucose levels, and diabetic incidence, while rs1862513 was associated with IR and T2DM." (PMID 36984867, 2023). "These two receptors might involve in resistin regulation of pro-inflammatory process and its association with cardiovascular diseases." (PMID 28525369, 2017). "Among them is resistin—a 12.5 kDa cysteine-rich protein that in humans is primarily secreted by the macrophages embedded in the adipose tissue—which has been implicated in cardiovascular disease and atherogenesis." (PMID 25811174, 2015). "Statin therapy may become another therapeutic strategy for controlling resistin-associated pathologic cardiovascular disease in humans." (PMID 19473519, 2009). "Furthermore, several clinical and epidemiological studies have revealed positive associations between plasma concentrations of resistin and proinflammatory cytokines, which are emerging risk factors for cardiovascular disease (CVD)." (PMID 19922611, 2009). "Furthermore, resistin could potentially serve as a biomarker for cardiovascular disease risk assessment." (PMID 40077669, 2025). "Future research must prioritize elucidating resistin’s full receptor signaling repertoire, defining isoform-specific functions, and validating its utility in multimodal biomarker panels to enhance risk stratification and pave the way for targeted therapies in cardiovascular diseases." (PMID 41347124, 2025). "Besides a role in metabolism, resistin has also been associated with cardiovascular diseases (CVD)." (PMID 28525369, 2017). "In our study, resistin was significantly associated with CIMT, particularly on the left carotid side, reinforcing its role in early vascular changes linked to cardiovascular disease." (PMID 40077669, 2025). "These interconnected networks position resistin as a nodal regulator linking inflammation, metabolic dysregulation, and structural remodeling in cardiovascular diseases." (PMID 41347124, 2025).
cardiovascular disease (continued). "Concurrently, integrating resistin into multimodal biomarker panels may enhance risk prediction models and provide a more comprehensive assessment of patient prognosis, ultimately paving the way for more personalized management strategies in cardiovascular diseases." (PMID 41347124, 2025). "Substantial evidence from both basic and clinical studies positions resistin as a critical adipokine at the intersection of metabolic dysfunction, chronic inflammation, and cardiovascular disease pathogenesis." (PMID 41347124, 2025). "While adipokines like adiponectin, apelin, and omentin have anti-inflammatory and cardioprotective properties, others like leptin, resistin, and visfatin exert pro-inflammatory effects, contributing to cardiovascular disease." (PMID 40362168, 2025). "Direct relationships between plasma levels of resistin and cardiovascular diseases have already been reported." (PMID 38164476, 2024). "Emerging evidence suggests that cardiovascular disease is accompanied by changes in serum resistin levels." (PMID 38255708, 2024). "Monocytes contribute to the development of T2DM and cardiovascular diseases by mediating the effects of resistin." (PMID 38951808, 2024). "Recently, Zhou (2020) highlighted the significant impact of resistin on the development of atherosclerosis and underscored its potential as a promising therapeutic target in the context of cardiovascular disease." (PMID 38255708, 2024). "High levels of resistin have been recorded in patients with cardiovascular disease and after major cardiovascular events." (PMID 39336454, 2024). "Our study clarified the potential clinical applications of Rb1 in the control of resistin-related vascular injury and in the treatment of cardiovascular disease." (PMID 37304947, 2023). "Among these associated protein-coding genes, MMP1, CTSB, POMC, RETN, and IL6R are known to be associated with SCAD or other cardiovascular diseases." (PMID 35425820, 2022). "For example, there is a positive correlation between resistin plasma levels and the incidence of cardiovascular events in patients with cardiovascular diseases." (PMID 34336840, 2021). "Inclinical and experimental studies, resistin has been suggested to be an independentinflammatory marker in cardiovascular diseases, especially in CAD and heartfailure." (PMID 27627223, 2016). "Emerging evidence suggest that cardiovascular disease is accompanied by changes in serum resistin levels." (PMID 24526524, 2014). "Age- and sex- or multivariate-adjusted odds ratios for cardiovascular diseases according to serum resistin quintiles." (PMID 19922611, 2009). "At the same time, some researchers have suggested links between resistin and oxidative stress, which is thought to be involved in the development of certain diseases, particularly cardiovascular disease." (PMID 17479165, 2007). "Proteomic analysis in a subcohort revealed that higher levels of inflammatory and endothelial-related proteins (e.g., IL-18, TNF-R1/2, CSF-1, thrombomodulin, resistin) correlated with higher UPF intake, many of which were prospectively linked to cardiovascular disease." (PMID 41010537, 2025). "Research suggests that resistin may modulate molecular signaling pathways involved in metabolic, inflammatory, autoimmune, and cardiovascular diseases." (PMID 39184804, 2024). "We tested the activity of the AMPK/mTOR signalling pathway, which is a potential target pathway of resistin in cardiovascular diseases, to further determine the molecular mechanism of H. parasuis-induced resistin in regulating claudin-5 and occludin expressions in PAECs." (PMID 36694280, 2023). "Thus, the results of this study provide a new insight to understand the relationship between the activity of sympathetic nervous system and cardiovascular diseases when plasma levels of resistin are high." (PMID 32440321, 2020).
cardiovascular disease (continued). "A recently published prospective cohort study showed that higher resistin is a significant predictor of cardiovascular diseases independent of conventional risk factors in individuals over 70 years." (PMID 29848323, 2018). "However, research on resistin has also been controversial in understanding their pathological relevance and its association with T2DM and cardiovascular diseases." (PMID 27608037, 2016). "On one hand we can speculate that, through its pro-inflammatory effect, resistin may well be deleterious on kidney function, quite similarly to what is believed for cardiovascular disease." (PMID 25811174, 2015). "Age- and sex-adjusted resistin values according to types of cardiovascular disease." (PMID 19922611, 2009). "It was reported that resistin could also play a significant role in the pathogenesis of angiogenesis-related vascular illnesses, hence potentially contributing to the development of cardiovascular disease and other angiogenic disorders." (PMID 38255708, 2024). "These activities support the hypothesis that resistin and cardiovascular disease." (PMID 28404934, 2017). "Thus, by means of epidemiological data, we tested the hypothesis that in human beings a resistin pathway does exist and does have a role on cardiovascular disease." (PMID 28290549, 2017). "Some non-CKD–MBD biomarkers, such as asymmetric dimethylarginine (ADMA), resistin, and C-reactive protein (CRP), were demonstrated to be related to a number of cardiovascular diseases." (PMID 40283096, 2025). "We examined relationships of leptin, resistin, TNF-α, and adiponectin with RV morphology and function (from cardiac MRI) in participants (n = 1,267) free of clinical cardiovascular disease from the Multi-Ethnic Study of Atherosclerosis (MESA)-RV study." (PMID 26348768, 2015). "In Korean subjects with T2D and CHD, serum resistin levels were significantly higher compared to those with T2D without a history of cardiovascular disease." (PMID 40283140, 2025). "In fact, previous research has confirmed that EAT participates in the occurrence and progression of cardiovascular diseases by synthesizing and secreting proinflammatory mediators and neurohormones such as IL-1β, IL-6, TNF-α, MCP-1, resistin, visfatin, and others." (PMID 38277087, 2024). "Additionally, resistin has been demonstrated to play a critical role in inflammation and intracellular ROS production of VSMCS that are closely relevant in the pathogenesis of cardiovascular disease." (PMID 37304947, 2023). "In metabolic and cardiovascular disease states, EAT reduces the production of cardioprotective adipocytokines, such as adiponectin, and induces the production of detrimental pro-inflammatory adipocytokines such as leptin, resistin, IL-6, tumor necrosis factor-α, and IL-17." (PMID 23409197, 2013).
tumor (90 papers, 2010 to 2026). "There was an inverse association between the levels of Resistin and miR-625 expressions that was significantly correlated with lymph node invasion and tumor stage in NSCLC patients." (PMID 38730433, 2024). "It has also been reported that a higher expression of resistin in tumor tissues is associated with the poor prognosis of CRC." (PMID 35890097, 2022). "Higher serum resistin has also been reported to be associated with worse tumor stage as we observed in our study and overall survival." (PMID 34876619, 2021). "Strongly positive resistin expression was associated with higher tumor grade (P < 0.001), ER (P < 0.001) and PR (P < 0.001) status, HER2 status (P = 0.001), and molecular classification (P < 0.001)." (PMID 33313320, 2020). "This is the first indication that adipokine resistin boosts VEGF-A-associated tumor angiogenesis via downregulation of miR-16-5p in vitro and in vivo." (PMID 30631040, 2019). "Patients with OSCC who had A/A homozygous of RETN rs3219175 polymorphism showed a high risk for an advanced tumor size (> T2), compared to those patients with G/G homozygotes." (PMID 30406149, 2018). "We found that high expression of resistin was significantly associated with tumor status and metastasis." (PMID 25404641, 2015). "The primary hypothesis of this study is that the IHC expression of adipokines—specifically leptin, leptin-R, adiponectin, and resistin—in RCC is associated with distinct tumor characteristics and may independently predict OS in patients undergoing nephrectomy." (PMID 41010935, 2025). "However, when the corresponding patients were divided into rectal and CRC, resistin was positively associated with tumor size and tumor grade, but only in patients diagnosed with rectal cancer, with a higher trend observed specifically in the male group." (PMID 39184804, 2024). "However, resistin is currently considered more likely a tumor marker than a risk factor in CRC patients and its role in colorectal carcinogenesis should be certified by future research." (PMID 37760840, 2023). "Moreover, some studies found that the higher serum level of resistin was directly associated with more clinicopathological characteristics including tumor grade, tumor size, lymph node metastasis, inflammation, and metabolism." (PMID 33517609, 2021). "Next, we examined whether overexpression of resistin-promoted tumor-associated angiogenesis in vivo." (PMID 30631040, 2019). "Interestingly, resistin seems also to be produced by tumors / tumor associated macrophages." (PMID 30517161, 2018). "Adipokines, such as leptin and resistin, stimulate tumor growth, while reduced adiponectin removes protective anti-inflammatory effects." (PMID 40732935, 2025). "A key area of interest is visfatin’s interaction with other adipokines (e.g., leptin, resistin, chemerin) and their combined effects on tumor progression." (PMID 40282553, 2025). "Elevated resistin concentrations have been observed in the serum or tumor tissue of CRC patients compared with healthy individuals." (PMID 39184804, 2024). "Leptin, Adiponectin, Nesfatin-1, Resistin, Chemerin, Visfatin: Mechanisms of action in tumor bone metastasis - Literature table." (PMID 38571500, 2024). "Numerous research studies have focused on investigating the effects of circulating resistin levels on CRC risk, progression, metastasis, invasion, tumor angiogenesis, and chemotherapy efficacy in CRC patients." (PMID 39184804, 2024). "Based on previous data indicating that resistin induces the secretion of MMPs, the role of resistin in tumor invasion was evaluated." (PMID 38137922, 2023). "Adipose tissue releases more than 20 different types of adipokines, including leptin, adiponectin, TNF-α, and resistin, which can promote tumor growth, proliferation, and metastasis." (PMID 38137922, 2023).